MSTN (myostatin)
Diseases named in the same sentence as MSTN in open-access papers (continued):
Sharing a sentence is not in itself a finding about the gene and the disease.
sarcopenia (continued). "Our study confirmed that myostatin may not be the primary cause of sarcopenia." (PMID 32927586, 2020). "Myostatin, activin A, and transforming growth factor (TGF)-β, bind activin type 2 receptor B (ActR2B) and induce sarcopenia by activating Smad2/3, which reduces the phosphorylation of Akt." (PMID 30754663, 2019). "Results here reported, highlighting the role of BMPs and myostatin pathways in physio-pathogenesis of human sarcopenia, allow us to propose human recombinant BMP-2/7 and anti-myostatin antibodies as a possible therapeutic option for sarcopenic patients." (PMID 28202082, 2017). "In this review, we summarize more recent therapeutic strategies (myostatin or proteasome inhibition, supplementation with eicosapentaenoic acid (EPA) or ursolic acid, etc.)for counteracting sarcopenia." (PMID 22500226, 2012). "To further explore the potential metabolic influence, we also compared sarcopenia-related parameters and circulating ApoJ and MSTN levels between individuals with and without DM." (PMID 40661742, 2025). "RA patients with sarcopenia had higher myostatin and lower irisin than RA patients without sarcopenia." (PMID 40593203, 2025). "AICAR has been shown to protect against sarcopenia, whereas metformin either failed to preserve muscle mass or induced muscle atrophy by upregulating myostatin." (PMID 41328324, 2025). "Among 182 RA patients (with three missing cases), myostatin levels were significantly higher in RA patients with sarcopenia than in RA patients without sarcopenia (P = 0.002)." (PMID 40593203, 2025). "Additionally, alterations in myostatin, insulin-like growth factor 1 (IGF-1), follistatin, and creatine kinase point to significant muscle involvement, consistent with sarcopenia, weakness, and functional decline in post–COVID-19 patients." (PMID 41439932, 2025). "Our results demonstrated that serum myostatin levels were significantly higher in RA patients with sarcopenia compared to those without sarcopenia (P = 0.002)." (PMID 40593203, 2025). "These revealed an association between ACTN3 and VDR gene variants and sarcopenia, while no such association was observed for IL6 variants and a specific MSTN variant linked to strength in athletes." (PMID 40772803, 2025). "Using the OsteoSarcopenia cohort, we performed a proteomic analysis of human plasma‐derived EVs to examine the relationships between sarcopenia biomarkers (myostatin, adiponectin, P3NP, CRP and TNF‐α) and sarcopenia‐related factors (muscle mass, muscle function and muscle performance)." (PMID 40162588, 2025). "Unlike conditions like muscular dystrophy, sarcopenia, and cancer cachexia, obesity and diabetes correlate with elevated serum levels of MSTN." (PMID 39340593, 2025). "ROC analysis suggested a good diagnostic yield of myostatin (AUC 0.79), IL-6 (AUC 0.67), and irisin (AUC 0.62) among dialysis patients (KTR were not included due to the very low prevalence of sarcopenia)." (PMID 39125361, 2024). "Myostatin and irisin levels were also analyzed in patients with type 2 diabetes mellitus with or without sarcopenia, as the incidence of sarcopenia increases in patients with diabetes." (PMID 38672282, 2024). "The best self-standing biomarkers of sarcopenia in dialysis patients were myostatin (AUC 0.789) and IL-6 (AUC 0.67); however, the latter was not retained in the final model." (PMID 39125361, 2024). "Myostatin stands out as a significant marker for malnutrition, MICS, and sarcopenia." (PMID 39125361, 2024). "When evaluating the risk of sarcopenia in the IBD patients based on ROC curves, it was not possible to assess the potential occurrence of sarcopenia by determining the levels of MSTN or Act A only." (PMID 38542721, 2024).
sarcopenia (continued). "On the other hand, genetic factors reported as sarcopenia biomarkers have also been identified such as angiotensin I-converting enzyme I (ACE), myostatin (MSTN), alpha actinin 3 (ACTN3), ciliary neurotrophic factor (CNTF), vitamin D receptor (VDR), insulin-like growth factor 1 (IGF1), and IL-6." (PMID 39194921, 2024). "In another study, disease-related malnourishment and subsequent sarcopenia correlated well with decreased irisin levels after age and sex adjustments but not with myostatin levels, which remained similar in sarcopenic and non-sarcopenic subjects." (PMID 39683624, 2024). "This corresponds with our previous research, which indicated that serum myostatin levels are not suitable biomarkers for sarcopenia in relatively healthy older adults, a revelation that bears relevance to the current study." (PMID 38641937, 2024). "This study showed significantly higher MSTN levels in patients with sarcopenia compared to those not affected by the condition." (PMID 38542721, 2024). "The effect of myostatin inhibitors on sarcopenia has been positive so far, but do not over-expect it." (PMID 37830636, 2023). "Validation of myostatin inhibitory antibodies in patients with sarcopenia has been positive, but excessive expectations are not warranted." (PMID 37830636, 2023). "For series 1, the group agreed on 4 biochemical markers that should be assessed in Phase II or Phase III trials (i.e., Myostatin-Follistatin, Brain Derived Neurotrophic Factor, N-terminal Type III Procollagen and Serum Creatinine to Serum Cystatin C Ratio – or the Sarcopenia Index)." (PMID 36633611, 2023). "We found that high IS levels were independent risk factors for sarcopenia in CKD, but myostatin levels were not." (PMID 36287929, 2022). "Serum myostatin and indoxyl sulfate (IS) levels increase with kidney function decline and may function as uremic toxins in chronic kidney disease (CKD)-related sarcopenia." (PMID 36287929, 2022). "Because older adults display co-existing factors related to sarcopenia, obesity and diabetes, they are particularly vulnerable to the negative effects of myostatin." (PMID 35287731, 2022). "In conclusion, IS levels are an important predictor of sarcopenia, while serum myostatin levels are not." (PMID 36287929, 2022). "Currently, no pharmaceutical treatment of sarcopenia exists, but potential therapies such as myostatin antibodies are being investigated in elderly." (PMID 35061818, 2022). "Our results showed elevated myostatin levels in the sarcopenia group than in the nonsarcopenia group." (PMID 35371569, 2022). "Sarcopenia is also related to changes in the levels of negative growth regulators, e.g., myostatin, and muscle protein degradation enzymes." (PMID 33418916, 2021). "Myostatin is an attractive therapeutic target for treatment of age- and CKD-related sarcopenia." (PMID 34063269, 2021). "Compared to healthy young men, there was no reported change in serum myostatin levels in an elderly population with mild or severe sarcopenia (as defined by muscular contractile force)." (PMID 33802348, 2021). "Although the inhibition of MSTN has not yet been applied in the treatment of sarcopenia diseases, MSTN and AAV–Cas9 are receiving more attention as potential therapeutic targets in this context." (PMID 32398787, 2020). "In men, on the other hand, myostatin appeared as a muscle mass homeostasis regulator, but not a major factor of sarcopenia." (PMID 32796600, 2020). "Hereby, the prognostic function of Myostatin levels especially in patients treated on a medical ICU and affected by sarcopenia could be further elucidated." (PMID 32784522, 2020). "Interestingly, many factors such as myostatin, TNF-α, IL-6, and ROS that are involved in the pathogenesis of sarcopenia are also regulators of bone remodeling, and thus are relevant for osteoporosis." (PMID 31068903, 2019).
sarcopenia (continued). "MSTN reduction remains a potential therapeutic option to treat sarcopenia and dynapenia, though it is no longer the only biologically-targeted option." (PMID 31751423, 2019). "Results here reported, highlighting the role of BMPs and myostatin pathways in physio-pathogenesis of human sarcopenia, allow us to propose human recombinant BMP-2/7 and anti-myostatin antibodies as a possible therapeutic option for the sarcopenia." (PMID 28202082, 2017). "In this study, myostatin levels were not related to SMM in the simple correlation study, but myostatin did increase the risk for pre-sarcopenia defined by hSMI in the logistic regression model." (PMID 26785759, 2016). "MSTN expression is increased in the skeletal muscle in patients with chronic kidney disease (CKD), which may play a role in the pathogenesis of sarcopenia or in the protein energy wasting (PEW)." (PMID 26502079, 2015). "As PEW or sarcopenia was not necessarily overt in those subjects, the present observation implied a potential physiological role of kidney in the regulation of MSTN." (PMID 26502079, 2015). "Plasma MSTN level was elevated in an early stage of CKD, which could be involved in the progression of sarcopenia." (PMID 26502079, 2015). "In conclusion, the present study indicated that the plasma MSTN level was elevated in early stages of CKD, which might contribute progression of sarcopenia in the elderly." (PMID 26502079, 2015). "In contrast, younger men had significantly higher absolute myostatin concentrations than older men without or with sarcopenia (both p < 0.001)." (PMID 26180626, 2015). "By contrast, younger men had higher myostatin concentrations than older men with and without sarcopenia." (PMID 26180626, 2015). "Myostatin inhibitor is the most advanced research with a Phase I/II trial in muscular dystrophy but does not try the possibility for attenuating sarcopenia." (PMID 22500226, 2012). "In this respect, high serum concentrations of myostatin-immunoreactive protein have been found in older women and men with muscle wasting (sarcopenia) however, so far the role of myostatin in aging-induced sarcopenia has not been determined." (PMID 19412331, 2007). "Furthermore, the study did not include circulating biomarkers commonly implicated in sarcopenia and cardiac cachexia, such as TNF-α, IL-6, or myostatin." (PMID 40566033, 2025). "In the group of HD and PD patients, those with sarcopenia were characterized by lower myostatin concentrations compared to non-sarcopenic patients (HD group: 2792.8 ± 1276 pg/mL vs. 4428.7 ± 2345 pg/mL; p < 0.001; PD group: 4358.7 ± 2388.8 pg/mL vs. 7436.5 ± 2475.2 pg/mL; p = 0.008)." (PMID 39125361, 2024). "Moreover, these diseases are accompanied by impaired muscle mass and strength, often not yet diagnosed as sarcopenia, but severe enough to result in reduced MSTN production in the muscles." (PMID 38542721, 2024). "Although nutritional supplements, hormonal therapies (e.g., IGF-1), exercise therapy, drug treatments (e.g., myostatin inhibitors), and anti-inflammatory agents have been used for the management of sarcopenia, no specific therapeutic agents for its treatment have been approved to date." (PMID 39451544, 2024). "The molecular mechanisms involved in this new onset acute sarcopenia are the atrogin-1/muscle atrophy F-Box (MaFbx)/muscle ring finger 1 (MuRF1) pathway, the insulin-like growth factor 1–protein kinase b–mammalian target of rapamycin (IGF-1-AKT-mTOR) and, principally, the myostatin pathway." (PMID 37408184, 2023). "Based on these results, antibody inhibition of myostatin may be effective in treating sarcopenia, but the results of many clinical trials do not support this notion." (PMID 37830636, 2023). "In addition, patients in the sarcopenia group had lower IGF-1 levels but higher myostatin and HOMA-IR levels than the nonsarcopenia group." (PMID 35371569, 2022). "Myostatin levels were similar between patients with and without sarcopenia (P = .108)." (PMID 34190188, 2021).
sarcopenia (continued). "Ageing appears to upregulate myostatin expression independent of adiposity, which if translated to increased myostatin protein secretion could contribute to sarcopenia by promoting atrophic and inhibiting hypertrophic pathways via canonical TGF-β signalling." (PMID 33528828, 2021). "Increased myostatin signaling has been hypothesized to play a major role in sarcopenia development, although no apparent increase in myostatin levels affects sarcopenic humans." (PMID 33401549, 2021). "However, the present study did not examine the myostatin levels and the association of myostatin with BCAA, IGF-1, and sarcopenia." (PMID 33050430, 2020). "Other myostatin inhibitors have been tested in patients with different muscle wasting conditions including sarcopenia, cachexia, and adult muscular dystrophies, but none have demonstrated the required efficacy in functional endpoints to allow regulatory approval." (PMID 29121992, 2017). "As blocking myostatin using antibodies has been shown to beneficially affect muscle mass and grip strength in mice and lean body mass and some functional parameters in old weak persons it is not surprising that myostatin is consistently included in any suggested set of biomarkers for sarcopenia." (PMID 26931422, 2016). "Third, we may not detect the expression pattern of myostatin during sarcopenia because of very small changes of this molecule at only a limited position of an organelle (e.g., satellite cells), but not throughout muscle fibers." (PMID 25221510, 2014). "These disparate findings suggest that myostatin may not be a primary driver of sarcopenia, or may instead highlight the complexities related to myostatin and its measurements." (PMID 25221510, 2014). "Studies indicated that myostatin release in the muscle is not necessary related to sarcopenia." (PMID 22934054, 2012). "These discrepancies indicate that myostatin may not be the primary trigger of sarcopenia." (PMID 39764565, 2025). "Collectively, these findings suggest that MSTN may serve not merely a negative regulator of muscle mass, but also as a potential biomarker of muscle function and quality in older adults with age-related sarcopenia." (PMID 40661742, 2025). "Furthermore, while the model utilizes easily accessible variables, the absence of more sophisticated biomarkers, such as serum myostatin or inflammatory markers, may restrict its ability to capture the complex biological processes driving sarcopenia." (PMID 40144877, 2025). "Of note, the larger muscle mass in myostatin KOs does not translate into increased strength, which might in part explain why pharmacological inhibition of myostatin signaling largely failed to mitigate functional impairments in muscle wasting diseases and sarcopenia." (PMID 34456749, 2021). "Recently, studies have introduced muscle-related biomarkers, including growth differentiation factor-15 (GDF-15), GDF-8 (myostatin), activin A, and follistatin that could be used as identifiable markers of sarcopenia, but a lack of studies may limit the confirmation of predictable biomarkers." (PMID 32927586, 2020). "In an early cross-sectional study, serum myostatin levels measured by radioimmunoassay (RIA) were reported to be significantly elevated with advancing age and declining lean mass, suggesting that myostatin may serve as a biomarker of sarcopenia in women and men." (PMID 26180626, 2015). "There is indeed evidence that myostatin null mice, although they have a doubling of muscle mass, have reduced specific force and may be actually prone to sarcopenia, suggesting that the intrinsic capacity to generate force is perturbed in the absence of myostatin." (PMID 25221510, 2014). "There were significantly lower levels of myostatin (80.6 pg/mL vs. 186.2 pg/mL; p = 0.0364) as well as activin A (32.1 pg/mL vs. 35.2 pg/mL; p = 0.0132) in the IBD patients with sarcopenia compared to those without sarcopenia." (PMID 38542721, 2024).
sarcopenia (continued). "There were significantly lower levels of MSTN (80.6 pg/mL vs. 186.2 pg/mL; p = 0.0364), as well as Act A (32.1 pg/mL vs. 35.2 pg/mL; p = 0.0132) in the IBD patients with sarcopenia compared to those without sarcopenia." (PMID 38542721, 2024). "Contrary to our expectations, stool zonulin, stool calprotectin and serum LBP, sCD14, IGF‐1, myostatin, FGF‐21, irisin and DAO were comparable in cirrhotic patients with and without sarcopenia and in controls with and without sarcopenia (P > 0.05)." (PMID 37767786, 2023). "IGF-1, myostatin, and HOMA-IR levels were divided into the nonsarcopenia, sarcopenia, and severe sarcopenia groups." (PMID 35371569, 2022). "Myostatin, a member of the TGF-β superfamily, has been extensively studied as another potential mediator of sarcopenia owing to its potent negative effects on cell growth and intracellular catabolic and anabolic signaling pathways." (PMID 34315961, 2021). "Myostatin levels and HOMA-IR in nonsarcopenia group were lower than sarcopenia and severe sarcopenia group (18.87 [13.48–20.87] vs 21.48 [16.1–33.33] vs 32.48 [21.38–38.90] ng/ml, p = 0.014) and 0.87 [0.56–1.33] vs 2.73 [1.88–2.96] vs 2.35 [1.93–2.72], respectively; p < 0.001)." (PMID 35371569, 2022).